AIRE (autoimmune regulator)
Description:
Transcription factor playing an essential role to promote self-tolerance in the thymus by regulating the expression of a wide array of self-antigens that have the commonality of being tissue-restricted in their expression pattern in the periphery, called tissue restricted antigens (TRA). Binds to G-doublets in an A/T-rich environment; the preferred motif is a tandem repeat of 5'-ATTGGTTA-3' combined with a 5'-TTATTA-3' box. Binds to nucleosomes (By similarity). Binds to chromatin and interacts selectively with histone H3 that is not methylated at 'Lys-4', not phosphorylated at 'Thr-3' and not methylated at 'Arg-2'. Functions as a sensor of histone H3 modifications that are important for the epigenetic regulation of gene expression. Mainly expressed by medullary thymic epithelial cells (mTECs), induces the expression of thousands of tissue-restricted proteins, which are presented on major histocompatibility complex class I (MHC-I) and MHC-II molecules to developing T-cells percolating through the thymic medulla. Also induces self-tolerance through other mechanisms such as the regulation of the mTEC differentiation program. Controls the medullary accumulation of thymic dendritic cells and the development of regulatory T-cell through the regulation of XCL1 expression. Regulates the production of CCR4 and CCR7 ligands in medullary thymic epithelial cells and alters the coordinated maturation and migration of thymocytes. In thimic B-cells, allows the presentation of licensing-dependent endogenous self-anitgen for negative selection. In secondary lymphoid organs, induces functional inactivation of CD4(+) T-cells. Expressed by a distinct bone marrow-derived population, induces self-tolerance through a mechanism that does not require regulatory T-cells and is resitant to innate inflammatory stimuli (By similarity).
Synonyms: APECED; PGA1; APS1; AIRE1; APSI
Tractability: No criterion of Open Targets' tractability assessment is met for any kind of drug.
Gene: Protein-coding gene on chromosome 21 (44,285,838 to 44,298,648, forward strand). Ensembl gene ENSG00000160224.
Subcellular location: Nucleus; Cytoplasm
Gene Ontology:
Molecular function: chromatin binding; histone binding; identical protein binding; protein binding; RNA polymerase II transcription regulatory region sequence-specific DNA binding; zinc ion binding; DNA binding; translation regulator activity
Biological process: central tolerance induction to self antigen; positive regulation of DNA-templated transcription; positive regulation of transcription by RNA polymerase II; regulation of DNA-templated transcription; humoral immune response; immune response; negative thymic T cell selection; peripheral T cell tolerance induction; positive regulation of chemokine production; regulation of thymocyte migration; thymus epithelium morphogenesis; regulation of translation; tolerance induction
Cellular component: cytoplasm; nucleus; nuclear body
Genetic constraint (gnomAD): Loss-of-function variants: 50 observed, 54.15 expected, observed/expected ratio (o/e) 0.92, 90% interval 0.74 to 1.17. The upper end of that interval is the gene's LOEUF score, 1.17, which puts it in group 5 of 6, group 1 being the genes least tolerant of losing a copy. Missense variants: 772 observed, 696.86 expected, observed/expected ratio (o/e) 1.11, 90% interval 1.04 to 1.18. Synonymous variants: 340 observed, 296.71 expected, observed/expected ratio (o/e) 1.15, 90% interval 1.05 to 1.25.
Gene-disease validity (ClinGen):
ClinGen rates the evidence that AIRE causes each of these diseases.
autoimmune polyendocrine syndrome type 1 (autosomal recessive): Definitive. Autoimmune polyendocrinopathy type 1, or APECED syndrome, is a genetic disease that manifests in childhood or early adolescence with a combination of chronic mucocutaneous candidiasis, hypoparathyroidism and autoimmune adrenal failure.
Homologues: Orthologues: chimpanzee AIRE (98% identical), macaque AIRE (86% identical), dog AIRE (79% identical), pig AIRE (79% identical), guinea pig AIRE (73% identical), mouse Aire (72% identical), rat Aire (71% identical), zebrafish aire (32% identical), tropical clawed frog aire (30% identical). Paralogues in human: PHF21A (15% identical), PHF21B (15% identical), ZMYND8 (12% identical), PHF12 (11% identical), ZMYND11 (7% identical).
Diseases named in the same sentence as AIRE in open-access papers:
AIRE is named in the same sentence as 134 diseases in open-access papers, as found by Europe PMC text mining. Sharing a sentence is not in itself a finding about the gene and the disease. The quoted sentences say what the papers report.
autoimmune polyendocrine syndrome type 1 (165 papers, 2005 to 2026). "Autoimmune polyendocrinopathy-candidiasis-ectodermal dystrophy (APECED) is caused by impaired central immune tolerance due to deficiency of the Autoimmune Regulator (AIRE) and is characterized by severe, multiorgan autoimmunity." (PMID 42051313, 2026). "Pathogenic variants in the gene encoding AIRE are causing Autoimmune polyendocrine syndrome type 1 (APS-1), defined by multiorgan autoimmunity and chronic mucocutaneous candidiasis." (PMID 40330469, 2025). "Autoimmune Polyendocrine Syndrome Type 1 (APS-I) results from mutations in the Autoimmune Regulator (AIRE) gene and serves as a valuable model to understand autoimmunity and immune deficiency." (PMID 40759705, 2025). "In humans, AIRE loss‐of‐function causes Autoimmune Polyendocrine Syndrome Type 1 (APS‐1) characterized by multi‐organ autoimmunity." (PMID 40558001, 2025). "Autoimmune polyendocrine syndrome type 1 is a rare monogenic disease caused by loss-of-function mutations in the AIRE gene, which result in the loss of thymic tolerance of T lymphocytes." (PMID 40495344, 2025). "Immune tolerance fails in autoimmune polyendocrine syndrome type 1 (APS-1) because of AIRE mutations." (PMID 38632993, 2024). "Mutations in the AIRE gene result in autoimmune polyendocrine syndrome type 1 (APS1), which presents with several clinical manifestations, including alopecia, one of the most frequently associated autoimmune disorders with the syndrome." (PMID 39459398, 2024). "Deficiency in the AIRE gene leads to autoimmune polyendocrinopathy-candidiasis-ectodermal dystrophy (APECED) syndrome." (PMID 38535602, 2024). "Loss-function mutations of AIRE in human also result in multiple organ-specific autoimmune diseases, such as autoimmune polyendocrinopathy-candidiasis-ectodermal dystrophy (APECED), otherwise known as autoimmune polyendocrine syndrome type 1 (APS-1)." (PMID 38562929, 2024). "Autoimmune polyendocrine syndrome type 1 (APS1, OMIM #240,300), also known as autoimmune polyendocrinopathy-candidiasis-ectodermal dystrophy is a rare autoimmune disease with mutations in the autoimmune regulator (AIRE) gene." (PMID 36944707, 2023). "Autoimmune polyendocrinopathy-candidiasis-ectodermal dystrophy (APECED) syndrome is a rare monogenic disease determined by biallelic mutations in AIRE gene, which encodes a transcription factor essential for central immune tolerance." (PMID 37457714, 2023). "AIRE (autoimmune regulator) gene mutations lead to the uncommon recessively inherited condition known as autoimmunity polyendocrinopathy candidiasis-ectodermal dystrophy (APECED)." (PMID 37809154, 2023). "For example, autoimmune polyendocrine syndrome type-1 (APS-1) caused by mutations in the gene autoimmune regulator (AIRE) has provided key insight into central tolerance." (PMID 35979360, 2022). "Loss of AIRE or functional mutations in humans has been reported to lead to the development of autoimmune diseases, such as autoimmune polyendocrinopathy-candidiasis ectodermal dystrophy and polyglandular syndrome type 1." (PMID 35464103, 2022). "The autoimmune regulator (Aire) gene was first described as the gene in which mutations caused APECED (autoimmune polyendocrinopathy-candidiasis-ectodermal dystrophy), a devastating rare genetic disorder that is characterized by a deregulated immune system." (PMID 36056452, 2022). "Autoimmune polyendocrinopathy-candidiasis-ectodermal dystrophy syndrome (APECED) is a rare autosomal recessive systemic autoimmune disease caused by mutations in the autoimmune regulator (AIRE) gene." (PMID 34991662, 2022). "APECED (Autoimmune-Polyendocrinopathy-Candidiasis-Ectodermal-Dystrophy) is a severe and incurable multiorgan autoimmune disease caused by mutations in the AIRE (autoimmune regulator) gene." (PMID 35432216, 2022).
autoimmune polyendocrine syndrome type 1 (continued). "Autoimmune polyendocrine syndrome type 1 (APS-1) is a rare monogenic inherited disease caused by mutations of the autoimmune regulator gene (AIRE) located on chromosome 21q22.3." (PMID 34344344, 2021). "Autoimmune polyendocrinopathy-candidiasis-ectodermal dystrophy (APECED), also known as autoimmune polyendocrine syndrome type 1, is a rare monogenic disorder caused by mutations in the autoimmune regulator gene (AIRE; OMIM 240300)." (PMID 34194389, 2021). "Autoimmune polyendocrinopathy-candidiasis-ectodermal-dystrophy (APECED) also known as autoimmune polyglandular syndrome Type 1 (APS-1) is a rare autosomal recessive disorder caused by mutations in the Autoimmune Regulator (AIRE) gene." (PMID 34078422, 2021). "Homozygous AIRE mutations cause Autoimmune Polyendocrinopathy Candidiasis Ectodermal Dystrophy (APECED)." (PMID 35058929, 2021). "In a murine model of AIH in the context of autoimmune-polyendocrine-syndrome-type-1, a multiorgan autoimmune condition caused by mutations of the autoimmune regulator (AIRE) gene, adoptive transfer of polyspecific Tregs was effective in treating AIH." (PMID 34650567, 2021). "Autoimmune polyendocrine syndrome type 1 (APS-1) is a rare monogenic inherited disease caused by mutations of the autoimmune regulator gene (AIRE)." (PMID 34344344, 2021). "It is known that mutations in AIRE cause the autoimmune polyendocrinopathy candidiasis ectodermal dystrophy (APECED): patients suffer from muscle disturbances that resemble those of limb-girdle myopathy." (PMID 33833239, 2021). "Congenital loss-of-function AIRE mutations lead to the severe dysimmune manifestations observed in autoimmune polyendocrine syndrome type 1 (APS-1): hypoparathyroidism, adrenal insufficiency and chronic mucocutaneous candidiasis." (PMID 33108502, 2021). "The fundamental nature of the defect in analogous AIRE mutations in mice results in a similar APECED syndrome accompanied by AIH, which is responsive to immunosuppressive therapy." (PMID 34948375, 2021). "Analogous to Aire-deficient mice, autoimmune polyendocrinopathy-candidiasis-ectodermal dystrophy (APECED) patients have mutations in the AIRE gene, resulting in autoimmunity affecting multiple endocrine glands." (PMID 33968086, 2021). "The autoimmune-poly-endocrinopathy-candidiasis–ectodermal-dystrophy/dyspla-sia (APECED) or autoimmune polyendocrine syndrome type 1 represents a rare monogenic autosomal recessive disease, which is induced by mutations in the AIRE gene." (PMID 34948375, 2021). "AIRE mutations lead to the development of autoimmune polyglandular syndrome type 1 while AIRE polymorphisms have been linked to organ-specific autoimmunity." (PMID 34621318, 2021). "The autoimmune polyglandular syndrome type 1 (APS1) is caused by pathogenic variants of the autoimmune regulator (AIRE) gene, located in the chromosomal region 21q22.3." (PMID 33717087, 2021). "Autoimmune polyendocrinopathy-candidiasis-ectodermal dystrophy (APECED) is a rare monogenic autosomal recessive disorder caused by mutation in the autoimmune regulator (AIRE) gene." (PMID 34122451, 2021). "Mutations in AIRE resulting in autoimmune polyglandular syndrome type 1 (APS1) are associated with the formation of autoantibodies against IL‐17A, IL‐17F, and IL‐22 and CMC." (PMID 32609955, 2020). "Humans with AIRE mutations develop Autoimmune Polyglandular Syndrome type-1 (APS-1) marked by multi-organ autoimmunity that includes T1D, Addison’s disease, and hypoparathyroidism." (PMID 33603744, 2020). "Autoimmune polyendocrinopathy-candidiasis-ectodermal dystrophy (APECED) is caused by recessive mutations in the AIRE gene." (PMID 32477345, 2020). "In humans, where AIRE expression is observed in the thymus and in dendritic cells (DCs), AIRE mutations cause a multi-systemic autoimmune syndrome, known as autoimmune polyendocrinopathy-candidiasis-ectodermal dystrophy (APECED)." (PMID 32784936, 2020).
autoimmune polyendocrine syndrome type 1 (continued). "•medullary thymic epithelial cells have defects in antigen presentation related to loss of expression of the transcription factor AIRE (autoimmune regulator), similar to that described in autoimmune polyendocrinopathy candidiasis ectodermal dystrophy." (PMID 35757304, 2019). "Mutations in AIRE results in autoimmune-polyendocrinopathy-candidiasis-ectodermal dystrophy (APECED) in which self-reactive T cells occur and alopecia is a common feature in about 40% of cases." (PMID 30941118, 2019). "Mutations in AIRE cause autoimmune polyglandular syndrome type 1 (APS-1), also known as autoimmune polyendocrinopathy-candidiasis-ectodermal dystrophy (APECED)." (PMID 30255105, 2018). "The presence of the novel c.396G>C (p.Arg132Ser) homozygous mutation of the AIRE gene confirms the diagnosis of APECED syndrome based on the new criteria." (PMID 30150985, 2018). "The autoimmune-poly-endocrinopathy-candidiasis–ectodermal-dystrophy/dysplasia (APECED) or autoimmune polyendocrine syndrome type 1 is a rare monogenic recessive autoimmune syndrome caused by mutations in the AIRE gene [reviewed in Ref." (PMID 30150985, 2018). "Autoimmune-polyendocrinopathy-candidiasis-ectodermal dystrophy (APECED) is a primary immunodeficiency caused by mutations in the autoimmune regulator gene (AIRE)." (PMID 29666621, 2018). "The loss of AIRE function associated with AIRE mutations is responsible for Autoimmune Polyendocrinopathy-Candidiasis-Ectodermal Dystrophy (APECED), a recognized polyendocrine syndrome with defective T and B cell tolerance." (PMID 30410491, 2018). "Autoimmune polyendocrinopathy-candidiasis-ectodermal-dystrophy (APECED) is a rare primary immunodeficiency disorder typically caused by homozygous AIRE gene mutation." (PMID 28257655, 2017). "Autoimmune polyendocrinopathy-candidiasis-ectodermal dystrophy (APECED) is a rare disorder caused by mutations in the autoimmune regulator (AIRE) gene, leading to defects in T cell selection." (PMID 31548517, 2017). "In humans, mutations in AIRE cause Autoimmune Polyendocrinopathy-Candidiasis-Ectodermal Dystrophy (APECED), which been associated with infertility in some patients through an elusive mechanism." (PMID 28742026, 2017). "Autoimmune polyendocrinopathy-candidiasis-ectodermal dystrophy syndrome (APECED) (OMIM ID: 240300) is an inherited rare autosomal recessive disorder caused by mutations of the AIRE (autoimmune regulator) gene." (PMID 27420045, 2016). "A clinical diagnosis of autoimmune polyglandular syndrome type 1 was made and confirmed with a pathogenic mutation in the autoimmune regulator (AIRE) gene." (PMID 27957353, 2016). "Autoimmune polyendocrinopathy-candidiasis-ectodermal dystrophy (APECED) is an autosomal recessive disorder caused by mutations in the autoimmune regulator (AIRE) gene and that is characterized by CMC, hypoparathyroidism and Addison's disease." (PMID 28080988, 2016). "Autoimmune regulator (Aire) mutations result in autoimmune polyendocrinopathy candidiasis ectodermal dystrophy (APECED), which manifests as multi-organ autoimmunity and chronic mucocutaneous candidiasis (CMC)." (PMID 27916941, 2016). "Autoimmune polyendocrinopathy candidiasis ectodermal dystrophy (APECED or APS-1) is a rare monogenic autoimmune disease caused by mutations in the autoimmune regulator (AIRE) gene." (PMID 25158603, 2014). "The AIRE gene was identified by positional cloning of a locus linked to a rare disease, Autoimmune-Polyendocrinopathy-Candidiasis-Ectodermal Dystrophy (APECED)." (PMID 24130560, 2013). "Expression of some TSAs requires a nuclear protein autoimmune regulator (AIRE), the dysfunctional mutations of which are responsible for an inherited human autoimmune disease, autoimmune polyendocrinopathy-candidiasis-ectodermal dystrophy (APECED)." (PMID 23986760, 2013). "By contrast, in autoimmune polyglandular syndrome type 1 (APS-1) caused by mutations in the AIRE gene, multiple autoimmune disorders are typical." (PMID 24198816, 2013).